EGFR (epidermal growth factor receptor)
Diseases named in the same sentence as EGFR in open-access papers (continued):
Sharing a sentence is not in itself a finding about the gene and the disease.
anaplastic thyroid carcinoma (12 papers, 2005 to 2023). "Previously, LAMC2 and EGFR were only found to co-localize on the cell membrane in anaplastic thyroid carcinoma cells." (PMID 37542131, 2023). "To investigate the biofunction of EGFR in anaplastic thyroid cancers, we analyzed the cell population in each cell cycle phase on EGFR sgRNA_2-transfected SW579 cells." (PMID 29849821, 2018). "Apigenin induces apoptosis in human anaplastic thyroid cancer cells through downregulation of both EGFR tyrosine autophosphorylation and phosphorylation of its downstream effector, mitogen activated protein (MAP) kinase." (PMID 28423637, 2017). "In conclusion, this study showed the inhibition of EGFR-mediated cell proliferation and the inhibition of tumour angiogenesis by gefitinib in anaplastic thyroid cancer cell lines." (PMID 15785737, 2005). "Specific EGFR stimulation with epidermal growth factor showed significant phosphorylation of ERK1/2 and Akt, and resulted in marked growth stimulation in an anaplastic thyroid cancer cell line, which highly expressed EGFR." (PMID 15785737, 2005). "Inhibition of EGFR-transmitted growth stimulation by gefitinib was clearly observed in anaplastic thyroid cancer cell lines." (PMID 15785737, 2005). "This study was undertaken to investigate the expression of EGFR in anaplastic thyroid cancer cell lines, and to explore the potential of therapies targeting EGFR as a new therapeutic approach." (PMID 15785737, 2005). "Previous studies by immunohistochemistry and EGF receptor assay have also found that EGFR was frequently overexpressed in anaplastic thyroid cancer." (PMID 15785737, 2005). "In this study, we demonstrated the expression of EGFR in anaplastic thyroid cancer cell lines and explored the potential therapeutic benefits of targeting this molecule with gefitinib." (PMID 15785737, 2005). "This is the first report to describe the potential of EGFR molecular-targeted therapy for treating anaplastic thyroid cancer." (PMID 15785737, 2005). "In the present study, we demonstrated that EGFR was almost universally expressed in anaplastic thyroid cancer cell lines, and that the level of its expression varied." (PMID 15785737, 2005). "Our results showed that preservation of the EGFR-mediated signal transduction pathway is a necessary condition for EGFR molecular-targeted therapy with gefitinib in anaplastic thyroid cancer cell lines." (PMID 15785737, 2005). "Also, in anaplastic thyroid carcinoma cell lines, constitutive activation of cMET was found simultaneously with elevated expression of EGFR." (PMID 27055285, 2016). "Our results suggest that the antitumour effects of gefitinib might offer a new therapeutic approach in anaplastic thyroid carcinoma when functional expression of EGFR is observed." (PMID 15785737, 2005). "Our results suggested that EGFR-targeted therapy, such as gefitinib, might be worth further investigation for the treatment of anaplastic thyroid cancer." (PMID 15785737, 2005). "For example, in anaplastic thyroid carcinoma, LAMC2 has been reported to bind EGFR to promote EGFR inactivation." (PMID 37542131, 2023).
astrocytic tumor (12 papers, 2010 to 2025). A glial tumor of the brain or spinal cord showing astrocytic differentiation. "NG2/CSPG4 expression was significantly associated with EGFR gene amplification (p = 0.0005) and poor prognosis (p = 0.016) in astrocytic tumors." (PMID 32599896, 2020). "The majority of tumors exhibited the 1p/19q-co-deletion (82%), while a minority of cases (18%) harbored molecular alterations frequently observed in high-grade astrocytic tumors (i.e., EGFR amplification, chromosome 10 loss)." (PMID 23071531, 2012). "The astrocytic tumors are prone to progress, and members of the epidermal growth factor receptor (EGFR) family have been linked to this malignant transformation." (PMID 20331873, 2010). "Rare combinations of histology and molecular features including oligodendroma, histologically noted glioblastoma tumors with unknown IDH1/2 status, or IDH-WT high-grade astrocytic tumors with wild-type EGFR or TERT promoter mutations were excluded from the analysis." (PMID 39553337, 2024). "The findings of our retrospective small cohort study suggest that in astrocytic tumors, PTEN mut/loss, EGFR mut/amp, and CDKN2A/B HD are strong MET accumulation factors, and NF1 mut/loss is a strong FDG accumulation factor." (PMID 40786409, 2025). "This study also revealed a significant association between EGFR mut/amp or PTEN mut/loss and MET accumulation in astrocytic tumors." (PMID 40786409, 2025). "Astrocytic tumors with CDKN2A/B homozygous deletions (HD), EGFR mutation and/or amplification (mut/amp), or PTEN mut/loss had a significantly higher T/N ratio on the MET-PET images compared with those without these alterations." (PMID 40786409, 2025). "EGFR is the most frequently amplified oncogene in astrocytic tumors; expression of genes SRI, NPTX2, MEST, RARRES2, and SEPTIN7 in association with GBM is reported in this study." (PMID 35327982, 2022). "We cannot rule out that a number of astrocytic tumors without IDH mutations may had EGFR amplification or chromosome copy number changes." (PMID 33184319, 2020).
dementia (12 papers, 2012 to 2025). Loss of intellectual abilities interfering with an individual's social and occupational functions. "EGFR has been linked to dementia, while mice with neuron-specific deletion of ELAVL1 have been reported to have a phenotype resembling motor neuron disease." (PMID 32327964, 2020). "HSP90AA1, involved in heat shock response (and its master regulator, i.e., HSF1), and EGFR are most important genes in pathology of dementia apart from KRs, given their presence as KRs as well as hubs in RN." (PMID 35327643, 2022). "The EGFR subunit ErbB4 and p-tauSer202 are overexpressed and colocalized in progressive supranuclear palsy (PSP), a form of dementia." (PMID 39434878, 2024). "Though the literature regarding the implication of EGFR in FTD, LBD, VD and HIV-associated dementia could not be found, it has an important role to play in aging-related metabolism." (PMID 35327643, 2022). "It has also been reported that EGFR is localized to the lumenal surface of endothelial cells and that EGFR immunoreactivity in brain vasculature was present in all assessed elderly patients with dementia, when compared to nondemented patients." (PMID 22754566, 2012).
dermatitis acneiform (12 papers, 2010 to 2025). "Prophylactic treatment with oral minocycline or doxycycline, moisturizers, and sunscreens has been reported to be beneficial for acneiform rash (AfR) caused by epidermal growth factor receptor (EGFR) inhibitors." (PMID 40503645, 2025). "Rash including acneiform dermatitis, paronychia, stomatitis, and diarrhea are associated with on-target anti-EGFR TKIs activity, while peripheral edema is associated with on-target anti-MET activity." (PMID 36979929, 2023). "Dermatologic reactions were commonly seen in CHRYSALIS trial with 86% of patients experiencing rash of any grade, including dermatitis acneiform, which is one of the most common on-target dermatological AEs associated with EGFR inhibitors." (PMID 36979929, 2023). "Although EGFR inhibitors improve patient survival, they are also associated with skin toxicity, including acneiform rash, xerosis, paronychia, and pruritus, and hair, eyelash, and mucosal changes." (PMID 32918131, 2021). "Acneiform rash (AfR) is an adverse event that occurs in response to a high number of epidermal growth factor receptor (EGFR) inhibitors." (PMID 40503645, 2025). "Among the 7 patients with severe dermatitis acneiform, 4 patients received first-line EGFR-TKI and anti-angiogenesis combination therapy." (PMID 35599308, 2022). "By contrast, the risk of acneiform dermatitis was markedly greater with Cetuximab, reaching 12-fold that of Nivolumab (ROR = 12.31), closely paralleling the high incidence of rash (≥80%) observed in the EXTREME trial, thereby confirming the skin-specific toxicity characteristic of EGFR inhibition." (PMID 41235256, 2025). "Acneiform dermatitis exhibited the most pronounced difference (86 cases with Cetuximab vs. 5 cases with Nivolumab), with an ROR of 12.31 (95% CI: 9.87–15.32), consistent with the well-documented mechanism of EGFR inhibitor–induced cutaneous toxicity." (PMID 41235256, 2025).
Erythema (12 papers, 2013 to 2025). Redness of the skin, caused by hyperemia of the capillaries in the lower layers of the skin. "Dermatological toxicities such as papulopustular rash (acneiform eruption), erythema, and skin fissures are common side effects of targeted cancer agents such as EGFR inhibitors, as EGFR is involved in the normal development and physiology of the epidermis." (PMID 27083443, 2016). "Topical treatment of mouse skin with the EGFR inhibitor AG1478 before UV exposure suppressed UV-induced erythema, edema, mast cell infiltration, and neutrophil infiltration." (PMID 23878744, 2013). "Thus, EGFR activation correlates positively with the macroscopic signs of skin edema and erythema following UV exposure." (PMID 23878744, 2013). "EGFR activation increased mast cell and neutrophil numbers in the skin, edema, and erythema, responses that may occur through both EGFR/p38 kinase/COX-2-dependent and independent mechanisms." (PMID 23878744, 2013). "We found that inhibition of EGFR suppressed UV-induced edema and erythema in mouse skin." (PMID 23878744, 2013). "To investigate the role of EGFR on the acute inflammatory response, we examined two macroscopic signs of acute UV-induced skin damage, erythema and edema, in mice topically treated with the EGFR inhibitor AG1478 or with the vehicle alone two hours prior to exposure to 10 kJ/m2 UVA/B." (PMID 23878744, 2013). "Within a few hours following a single UV exposure, skin erythema developed in both EGFR inhibitor- and vehicle-treated mice (data not shown)." (PMID 23878744, 2013).
hyperlipidemia (12 papers, 2015 to 2025). "EGFR inhibition is also associated with improved hyperlipidemia." (PMID 34944593, 2021). "Among patients with EGFR‐TKI treatment, hyperlipidemia and radiation therapy were associated with increased WMH (hyperlipidemia: aRR 1.65 [95% CI 1.01−2.70], p = .047; radiation therapy: aRR 2.37 [95% CI 1.51−3.71], p = .010)." (PMID 38054663, 2023). "We also shed light on the understanding of how hyperlipidemia and saturated fatty acids can activate the EGFR signaling pathway through TLR4 and c-Src/EGFR complex." (PMID 27014908, 2016). "EGFR also contributes to hyperlipidemia-induced cardiac inflammation." (PMID 27087279, 2016). "The aim of this study was to determine the role of EGFR in hyperlipidemia-induced cardiac damage." (PMID 27087279, 2016). "In NRK-52E cells, we also elucidated the mechanism behind hyperlipidemia-induced EGFR activation." (PMID 27014908, 2016). "Furthermore, treatment of N2a cells with statins, which impair cholesterol biosynthesis and are widely used in the treatment of hyperlipidemia, resulted in phosphorylation of EGFR and downstream kinases such as PI3K and Akt55." (PMID 26687764, 2015). "However, blocking of EGFR is found to be a suitable strategy to control hyperlipidemia." (PMID 34944593, 2021). "Thus, our observations demonstrated that EGFR inhibition could reduce hyperlipidemia levels, as well as inhibit hyperlipidemia-induced renal tissue injury." (PMID 27014908, 2016). "The hyperlipidemia-triggered metastatic ability of CRC cells under treatments of antioxidants, statin, and cetuximab or knockdown of IL-8, KRAS, and EGFR was evaluated in vitro and in vivo." (PMID 37649607, 2023). "Briefly, hyperlipidemia/FFAs activate TLR4, resulting in the phosphorylation of c-Src and then EGFR in c-Src/EGFR complex and subsequent activation of AKT and ERK." (PMID 27014908, 2016).
Interstitial pneumonitis (12 papers, 2014 to 2025). "Reports of interstitial pneumonitis with EGFR inhibitors like gefitinib and erlotinib are present in the literature, but pulmonary toxicity with cetuximab has rarely been reported." (PMID 39618678, 2024). "There were 70 patients treated with EGFR-TKI plus nivolumab, of which 18 patients (25.7%) developed interstitial pneumonitis and 15 of these 18 patients were treated with EGFR-TKI after nivolumab." (PMID 37345194, 2023). "Others have reported severe interstitial pneumonitis with concurrent irradiation-gefitinib (or other anti-EGFR)." (PMID 27764781, 2017). "In the standard care group, 20% of patients stopped using EGFR TKIs after respiratory failure because it was ineffective or because of interstitial pneumonitis." (PMID 25050082, 2014). "According to our study results, it is worth administering EGFR-TKIs for patients who are detected as EGFR mutation while they are undergoing MV in ICU, and TKI should be withheld if there is any suspicion of TKI-related interstitial pneumonitis clinically." (PMID 34680533, 2021). "An observational study including 20,516 patients with NSCLC investigated the incidence of interstitial pneumonitis in patients treated with EGFR-TKI, nivolumab, and EGFR-TKI plus nivolumab." (PMID 37345194, 2023). "The EGFR and ALK dual inhibitor brigatinib reportedly induced similar early‐onset drug related interstitial pneumonitis." (PMID 33438350, 2021). "No cases of interstitial pneumonitis were reported following EGFR TKI rechallenge." (PMID 39715697, 2025).
lung neoplasm (12 papers, 2015 to 2025). A benign or malignant, primary or metastatic neoplasm involving the lungs. "More than half of lung tumours express receptors from EGFR family and one-fifth of lung tumours carry EGFR mutations, causing proliferation, migration, and metastasis." (PMID 29062084, 2017). "Among the five patients with double common EGFR mutations (19Del plus L858R), only one stage IV patient with brain metastases exhibited effective local control, i.e., SD in response to gefitinib, but progression of the primary pulmonary neoplasm was identified after 7.9 months." (PMID 30055651, 2018). "Accordingly, EGFR and COX-2/TNF-α activation/induction is expected to play important roles in MGL deficiency-driven lung tumors." (PMID 29348400, 2018). "It is tempting to hypothesize that LOH of FLCN, concomitant with oncogenic mutations in EGFR or KRAS, might allow low-grade lung neoplasms to progress to invasive adenocarcinomas." (PMID 26974543, 2016). "The EGFR gene of the gastric metastasis harbored a 19th exon mutation, identified by the Amplified Refractory Mutation System method, which detects single base pair mutations in a background of wild-type DNA, while the primary lung tumor showed a wild-type EGFR sequence." (PMID 25663915, 2015). "Despite the occurrence of EGFR mutations that improve the prognosis of primary lung neoplasm, such an association could not be confirmed in these studies concerning EGFR-positive BMs." (PMID 37240478, 2023). "In pulmonary neoplasms, the NGS panels allow us to investigate multiple targets beyond the EGFR and to increase analytical predictivity and effectiveness." (PMID 37457625, 2023). "It has been summarized that arsenic-induced lung tumours may, through disruption of the PI3K/AKT signalling pathway, activate the EGFR signalling pathway and affect the NRF2 signalling pathway to play a role in carcinogenesis." (PMID 32457348, 2020).
Nephropathy (12 papers, 2013 to 2025). A nonspecific term referring to disease or damage of the kidneys. "The results showed that severe kidney damage causes prolonged activation of EGFR which is essential for the recovery of renal tubular cells in the initial phase (the first 2 days), but this sustained EGFR activation would lead to fibrogenesis after 28 days." (PMID 39234105, 2024). "In comparison, the non‐third‐generation EGFR‐TKIs group reported liver damage (2 patients, 5.4%), kidney damage (1 patient, 2.7%), and bone marrow suppression (3 patients, 8.1%)." (PMID 41399957, 2025). "The aim of this review is to summarize the contribution of EGFR pathway activation in experimental kidney damage, with special attention to the regulation of the inflammatory response and the role of some EGFR ligands in this process." (PMID 30670929, 2018). "All these studies show the complexity of EGFR pathway activation and its involvement in the pathogenesis of kidney damage." (PMID 30670929, 2018). "Previous studies have demonstrated the role of EGF/EGFR in various nephropathies." (PMID 33921219, 2021). "The transactivation of EGFR increases the possibility of EGF/EGFR being involved in the nephropathy related to TKIs, since the metabolites of the damaged endothelial cells may lead to podocyte injury through this way." (PMID 33921219, 2021). "The authors suggested a role of TGF-α as a key factor between AII signaling and EGFR transactivation during AII-induced nephropathy, regardless of blood pressure levels." (PMID 33469545, 2020). "The role of the EGFR pathway, involving Pi3-AKT-Rac1, in cisplatin-induced nephropathy, could not be substantiated in further detail." (PMID 23457647, 2013).
primary immunodeficiency (12 papers, 2019 to 2025). "The results showed that these lncRNAs were involved in various immune responses, antigen processing, and presentation, T cell receptor signaling pathway, EGFR signaling pathway, ERBB signaling pathway, ECM receptor interaction, focal adhesion, and primary immunodeficiency." (PMID 34374227, 2021).